HOXD10 (homeobox D10)
Diseases named in the same sentence as HOXD10 in open-access papers (continued):
Sharing a sentence is not in itself a finding about the gene and the disease.
cancer (53 papers, 2009 to 2025). A tumor composed of atypical neoplastic, often pleomorphic cells that invade other tissues. "For instance, alterations in the HOX family members HOXA5 and HOXD10 have been implicated in the development and progression of cancer." (PMID 37812190, 2023). "Research has suggested that microRNAs such as miR-501 and miR-376b can modulate HOXD10 expression, potentially influencing cancer progression." (PMID 40148674, 2025). "This study consisted of 98 patients in whom HOXD10 expression was found to be decreased in PTC tissue compared to para-cancer tissues using IHC." (PMID 39858044, 2025). "HOXA1, HOXC13 and HOXD10 were significantly correlated with the cancer hallmarks driving oral carcinogenesis." (PMID 40676709, 2025). "HOXD10 is abnormally expressed in many malignant tumors, including breast, bladder, ovarian, and colon cancers 5-7." (PMID 38356716, 2024). "HOXD10 was reported to be associated with the epithelial-mesenchymal transition (EMT), which plays a central role in cancer progression, metastasis and drug resistance, and induced by inflammation." (PMID 38356716, 2024). "Focusing on the statistically significant hypermethylated DMRs overlapping homeobox genes, the set of homeobox genes hypermethylated in all 16 TCGA cancer types were the HOXD10 and HOXA3 genes." (PMID 38886487, 2024). "We identified two homeobox genes, HOXA3 and HOXD10, that are hypermethylated in all 16 cancer types." (PMID 38886487, 2024). "Overall, our findings suggest that gastrodin acts as an anti-cancer agent by inducing ferroptosis and inhibiting cell proliferation in HOXD10/ACSL4-dependent pathways." (PMID 38138552, 2023). "On this basis, it seems that the role of HOX genes in cancer is predominantly pro‐oncogenic, with the exception only of HOXD10." (PMID 35080776, 2022). "Accumulating evidence indicates that homeobox D10 (HOXD10) acts as a tumor suppressor or oncogene in various carcinomas." (PMID 34825321, 2022). "Emerging evidence suggests that hypermethylation of HOXD10 plays an important role in human cancers." (PMID 34790580, 2021). "HOXD10-expressing cells showed a remarkably impaired migration and invasion ability in both cancer cell lines compared with that in control cells." (PMID 34790580, 2021). "Homeobox D10 (HOXD10) is a member of the homeobox gene family that serves as a key transcription factor in the development of various types of cancer." (PMID 34790580, 2021). "To analyze the impact of miR-10b on its targetome, we first screened the scientific literature in an automated text-mining approach for miR-10b in cancer, which highlighted the previously reported, direct miR-10b target transcription factor HOXD10." (PMID 32276641, 2020). "HOXD10 protein level was evaluated in carcinoma or para-carcinoma tissue from patients with CRC via immunohistochemistry (IHC) in order to investigate how HOXD10 had an effect on CRC." (PMID 30683109, 2019). "Dysregulation of HomeoboxD10 (HOXD10) was found to suppress or promote cancer progression in different cancer types." (PMID 29075359, 2017). "This study aims to investigate the effect of miR-10b overexpression on cancer cell proliferation, migration, invasion, and Hoxd10 expression." (PMID 26311318, 2015). "Majority of CaCx cases portrayed HOTAIR down-regulation in comparison to HPV negative controls, with corresponding up-regulation of HOTAIR target, HOXD10, and enrichment of cancer related pathways." (PMID 26152361, 2015). "Additionally, HOXD10 is known to undergo extensive methylation in various cancers, leading to gene silencing." (PMID 40148674, 2025). "Notably, HOXA1, HOXC13 and HOXD10 were strongly correlated with cancer hallmarks, indicating their regulatory role in carcinogenesis." (PMID 40676709, 2025).
cancer (continued). "The detailed regulatory mechanism that links HOXD10 and the oxidative phosphorylation genes is not yet fully understood, our findings provide novel insight into HOXD10-mediated pathways and their effects on cancer metabolism, carcinogenesis, and the progression of EOC." (PMID 38356716, 2024). "HOXD11 and HOXD10, being homologous proteins, play distinct roles in cancer biology." (PMID 39428922, 2024). "A low level of HOXD10 promotes the invasion and metastasis of cancer cells." (PMID 38139352, 2023). "The aberrant expression of HOXD10 has been observed in various cancers, such as ovarian cancer, prostate cancer, endometrial cancer, esophageal squamous cell carcinoma, colon cancer, and glioblastoma through regulatory activities like metastasis in cancers and tumor cell proliferation." (PMID 37663424, 2023). "HOXD10 has been identified as a suppressor in multiple cancer types." (PMID 38138552, 2023). "Disrupting this regulatory axis with HOXD10 significantly alleviated the phenotype of BAP31 overexpression-induced CRC lung metastasis, providing further insight into the molecular mechanism underlying BAP31-involved cancer progression." (PMID 38069061, 2023). "Furthermore, cancer tissues with methylated HOXD10 revealed low expressions of both miR-7 and IGFBP3 (p < 0.01)." (PMID 34790580, 2021). "Furthermore, suppression of HOXD10 by miR-10b and miR-1269 was able to promote cancer metastasis in CRC." (PMID 34790580, 2021). "We evaluated the methylation level of HOXD10 in paired cancer and normal tissues (n = 42) by using pyrosequencing, followed by validation of the methylation status of HOXD10 from The Cancer Genome Atlas (TCGA) datasets with 302 cancer tissues and 38 normal tissues." (PMID 34790580, 2021). "HOXD10 is a transcription factor whose expression is altered in many cancers." (PMID 33245713, 2020). "Thus, HOXD10 was aberrantly hypermethylated in various carcinoma, which showed the potential of it as biomarker or therapeutic target." (PMID 30683109, 2019). "The Cell proliferation, migration, invasion and apoptosis were respectively measured by MTT assay, transwell assay, wound healing assay and flow cytometry assay in carcinoma cell lines after treated with 5-aza-2′-deoxycytidine (5-Aza-dC) or transfected with HOXD10-expressing plasmid." (PMID 30683109, 2019). "Besides, a differentially methylated region 540(DMR_540) of HOXD10 indicated the remarkable difference in normal group and carcinoma group which had a higher value than the normal group." (PMID 30683109, 2019). "The HOXD10 stainings are strong, strong, moderate and weak in para-carcinoma (× 100), well- (× 400), moderately- (× 400) and poorly-differentiated carcinoma (× 400), respectively, while the RHOC stainings are weak, weak, moderate and strong in the same carcinoma groups, respectively." (PMID 30683109, 2019). "miR10b is a transcriptional target of Twist1 in cancer cells and is involved in repression of Hoxd10 expression, suggesting that Twist1 may regulate Hoxd10 expression via control of this miRNA." (PMID 24893291, 2014). "Additionally, HOXD10 appears to suppress tumors in a variety of cancers in humans." (PMID 38138552, 2023). "In view of recent limited evidence that HOXD10 methylation contributes to gene regulation and carcinogenesis, in the present study, we first revealed that HOXD10 was differentially methylated between cancer and normal tissues, which was observed from both TCGA dataset and our cohort." (PMID 34790580, 2021). "miR-1269a can regulate the occurrence and development of cancer by targeting downstream genes (CXCL9, SOX6, FOXO1, ATRX, RASSF9, SMAD7, HOXD10, and VASH1)." (PMID 35252180, 2022). "Many homeobox genes are found hypermethylated in different cancer types, including HOXD1 and HOXD10 that are also identified in this study." (PMID 36447287, 2022).
cancer (continued). "The involvement of HOXD10, HOXD11, HOXD1, HOXC4, HOXC10, and HOXA11, in the cell cycle and the EMT, confirm their role in the cancer-related signaling pathways." (PMID 35562533, 2022). "MiRs in the cancer exosomes inhibit the expression of their respective mRNA targets, PTEN, and HOXD10 in recipient epithelial cells." (PMID 31537868, 2019). "The fact that Hox genes such as HOXD10, HOXA9, HOXD9, HOXD13 are strongly upregulated in Huh6 cells on the CAM reflect a profound reprogramming of cancer cells in a permissive, growth promoting in vivo microenvironment." (PMID 29662633, 2018). "Its overexpression induces an aggressive phenotype in many cancers and aberrant expression of homeotic HOX transcription factors, especially HOXD10, that regulate differentiation and tissue homeostasis." (PMID 25994132, 2015). "MiR-10b inhibits the synthesis of the HOXD10 protein and permits the expression of the pro-metastatic gene product RHOC, which in turn favors cancer cell migration and invasion." (PMID 21826246, 2011). "The downregulation of HOXD10 permits subsequently the expression of the prometastatic gene product RHOC, favoring, in turn, cancer cell migration and invasion." (PMID 19664288, 2009). "HOXD10, a member of the homeobox (HOX) superfamily, plays a crucial role in cell differentiation and morphogenesis and acts as a key transcription factor in various cancers." (PMID 40148674, 2025). "HOXA1, HOXD10 and HOXC13 are strongly correlated with cancer hallmarks." (PMID 40676709, 2025). "Although these findings showed that HOXD10 serves as a key regulator in cancer metastasis, the clinical and biological relevance of HOXD10 in CRC is not fully investigated." (PMID 34790580, 2021). "The results showed that some HOX genes in pan-cancer had significant strong correlation (R≥0.8): HOXA9 with HOXA10, HOXB5 with HOXB6 and HOXB8, HOXB8 with HOXB6 and HOXB9, HOXB3 with HOXB4 and HOXB5 and HOXB6, HOXC8 with HOXC9, HOXC9 with HOXC10, HOXD10 with HOXD11." (PMID 39980564, 2025). "Analysis of DEHGs in oncogenic pathways using GSCALite26 indicated that HOXD10, HOXD11, HOXD1, HOXC4, HOXC10, and HOXA11 may have a crucial role in the activation of epithelial-mesenchymal transition (EMT) in cancer, represented in the form of heatmap percentage." (PMID 35562533, 2022). "Notably, although the phenotypical changes elicited by HOTAIR in VM-CUB1 were similar to those reported in other cancer cells, they took place in the absence of changes in HOXD10 expression, demonstrating that HOXD10 is not a general essential mediator of these effects." (PMID 25994132, 2015).
infection (1 paper, 2018). The state of being infected such as from the introduction of a foreign agent such as serum, vaccine, antigenic substance or organism. "(B) Lentiviral infection efficiency of MCF-7 cells stably depleted of STARD13, CDH5, HOXD1, and HOXD10 was verified by Western blot analysis." (PMID 29848346, 2018). "(A) Lentiviral infection efficiency of MDA-MB-231 cells stably expressing STARD13-3′UTR, CDH5-3′UTR, HOXD1-3′UTR, and HOXD10-3′UTR was examined by qRT-PCR." (PMID 29848346, 2018).
HOXD10 also shares sentences with these, for which no sentence is quoted: astrocytoma (3 papers); colon adenocarcinoma (3); oral squamous cell carcinoma (3); acute myeloid leukemia (2); adenosquamous carcinoma (1); breast (1); Charcot-Marie-Tooth disease (1); Cirrhosis (1); dysplasia (1); endometrial adenocarcinoma (1); endometrioid ovarian cancer (1); Gynecomastia (1); inflammatory breast carcinoma (1); laryngeal carcinoma (1); leukemia (1); lymphoma (1); male breast carcinoma (1); malignant glioma (1); metastatic melanoma (1); non-small cell lung carcinoma (1); oligodendroglioma (1); osteosarcoma (1); penile squamous cell carcinoma (1); renal carcinoma (1); renal fibrosis (1); small cell lung carcinoma (1); squamous cell carcinoma (1); stem cell leukemia (1); teratoma (1); ulcerative colitis (1).